FSHR (follicle stimulating hormone receptor)
Diseases named in the same sentence as FSHR in open-access papers (continued):
Sharing a sentence is not in itself a finding about the gene and the disease.
polycystic ovary syndrome (24 papers, 2014 to 2025). A disorder that manifests as multiple cysts on the ovaries. "FSHR has additionally been associated with breast cancer, polycystic ovaries but also thyroid cancer (rs34201686, in moderate linkage disequilibrium (LD) with our top SNP, rs12713034, r2 = 0.363) and asthma in the UK Biobank." (PMID 30926877, 2019). "For instance, the heterozygous A307T variation (minor allele frequency [MAF]: 0.49) in the follicle stimulating hormone receptor (FSHR) is prevalent in women who develop polycystic ovary syndrome and is associated with a higher responsiveness to exogenous FSH." (PMID 29249361, 2018). "Studies in Caucasians suggest that certain FSHR variants are more common in women with polycystic ovary syndrome (PCOS) than normal women." (PMID 25179311, 2014). "The FSHR polymorphism’s impact on women’s reproductive function has been demonstrated in several studies; particularly in some diseases, such as the polycystic ovary syndrome and amenorrhea." (PMID 29954364, 2018). "Dysfunction of VSELs/OSCs (which express ERα, ERβ, FSHR) due to neonatal exposure to endocrine disruption results in ovarian insufficiency and polycystic ovaries." (PMID 36726163, 2023). "As yet, we know little about FSHR expression in follicles of women with PCOS but it is noteworthy that cultured granulosa cells from small antral follicles in polycystic ovaries are hyper-responsive to FSH in terms of estradiol production." (PMID 30147675, 2018). "Basic research on polycystic ovary syndrome (PCOS), which is often associated with high AMH levels, has suggested a relationship between FSHR polymorphism and poor follicular development." (PMID 40051953, 2025). "While abnormal levels of androgens as for instance in women with polycystic ovaries affects and may attenuate follicular development, normal physiological levels of androgens support follicular growth and development prior to follicular selection potentially via enhanced FSHR expression." (PMID 41029688, 2025). "Next, we checked the FSHR expression levels in visceral (VAT) and subcutaneous (SCAT) adipose tissue samples from obese and lean women, VAT from women with polycystic ovary syndrome (PCOS), and adipocytes isolated from VAT and SCAT." (PMID 39633277, 2024). "Other studies demonstrated decreased expression of FSHR and CYP11A1 and increased expression of CYP19A1, STAR, HSD3B2 and INHBA in polycystic ovary granulosa cells compared to controls." (PMID 36768772, 2023). "FSHR genotypes were also evaluated in a cross-sectional study among 178 women (148 normogonadotropic anovulatory women, of whom 61 had polycystic ovary syndrome [PCOS], and 30 normo-ovulatory controls)." (PMID 35178027, 2021). "Prolonged exposure of GCs derived from polycystic ovaries to high levels of AMH has been revealed to affect the expression patterns of aromatase and FSHR and disrupt SMAD signaling by increasing the level of I-SMAD-6, -7, and diminishing activation of SMAD-1/5/8 and co-SMAD-4." (PMID 36611967, 2022). "PCOS: polycystic ovary syndrome; FSHR: follicle-stimulating hormone receptor; ESR1: estrogen receptor 1; IVF: in vitro fertilization; rhFSH: recombinant human follicle-stimulating hormone; MII: metaphase II; MI: metaphase I; GV: germinal vesicle." (PMID 37012960, 2023).
endometriosis (17 papers, 2012 to 2025). The growth of functional endometrial tissue in anatomic sites outside the uterine body. "G-protein coupled receptors that bind FSH (FSHR) are expressed in the granulosa cells, and there are reports that FSHR polymorphisms are associated with increased risk of endometriosis in fertile women." (PMID 35514537, 2022). "Incidentally, the FSHR polymorphism has been reported to be associated with the risk of developing endometriosis and the fertility status of patients." (PMID 35330066, 2022). "In this study, we aimed to evaluate the effects of FSHB:c.-211G>T, FSHR:c.919G>A, and FSHR:c.2039G>A variants, alone and combined, on the hormonal profile and reproduction outcomes of women with endometriosis." (PMID 34659133, 2021). "Characteristics of women with endometriosis according to genetic models and genotypes of the variants c.919G>A and c.2039G>A of the FSHR gene." (PMID 34659133, 2021). "Analysis of the interaction model between the FSHB:c.-211G>T, FSHR:c.919G>A and FSHR:c.2039G>A variants in women with endometriosis, according to the MB-MDR model." (PMID 34659133, 2021). "The A allele of the FSHR:c.919G>A SNV was associated with a lower number of oocytes retrieved in women with moderate/severe endometriosis and the GA genotype was associated with higher FSH levels in overall endometriosis." (PMID 34659133, 2021). "FSHR has been reported to be expressed in the endometrium, and aberrantly expressed in endometriosis, a condition that increases risk of EC." (PMID 35185785, 2021). "Aberrant expression of FSHR has been linked to endometriosis, a disease which increases the risk to women of developing EC." (PMID 35185785, 2021). "Inspired by these findings, we aimed to evaluate the effects of FSHB:c.-211G>T, FSHR:c.919G>A, and FSHR:c.2039G>A variants, alone and combined, on the hormonal profile and reproduction outcomes of women with endometriosis." (PMID 34659133, 2021). "Homozygous FSHR polymorphism Asn680 have protective effects on development of endometriosis in Chinese women." (PMID 34717708, 2021). "The genotype frequencies of the FSHB and FSHR variants in Brazilian women with endometriosis." (PMID 34659133, 2021). "Interestingly, the findings were quite different considering the effect of the FSHR:c.2039G>A variant on endometriosis stage." (PMID 34659133, 2021). "Collectively, the GG homozygous genotype of polymorphism of HSD17B3 (289Gly/Gly) (wild type) may play a crucial role in the development of endometriosis in the presence of AA homozygous genotype of polymorphism of FSHR (680Asn/Asn) (wild type)." (PMID 23139742, 2012). "Similarly, a significantly decreased risk for endometriosis was found in women who had at least a mutant allele of FSHR (genotype GG+GA, 680Ser/Ser+680Ser/Asn) and CYP19 (genotype TT+TC, 264Cys/Cys+264Cys/Arg) (P = 0.01; OR = 0.66)." (PMID 23139742, 2012). "Furthermore, a significantly decreased risk for endometriosis was also observed in women who had at least a mutant allele in FSHR at position 680 (genotype GG+GA, 680Ser/Ser+680Ser/Asn) and position 307 (genotype GG+GA, 307Ala/Ala+307Ala/Thr) (P = 0.01; OR = 0.66)." (PMID 23139742, 2012). "FSHR:c.919G>A SNV affects FSH levels in women with overall endometriosis and the number of oocytes retrieved in those with moderate/severe endometriosis, while the FSHR:c.2039G>A SNV affected FSH levels in women with overall endometriosis." (PMID 37959232, 2023). "FSHR 680Ser-Ser/GG genotype and ‘‘GG/307Ala680Ser’’ haplotype were more frequently found in fertile women with endometriosis, while the presence of "GA/307Ala680Asn" haplotype lowers the likelihood of disease onset and progression." (PMID 34405378, 2022). "Various uteropathies have a stem cell basis and this explains FSHR expression in clinical samples of endometriosis, endometrial cancers as well as myomas." (PMID 34717703, 2021).
endometriosis (continued). "Direct comparison of paired eutopic endometrium and ectopic lesions of patients with endometriosis found all ectopic endometrium aberrantly expressed FSHR, and half of eutopic endometrium had aberrant FSHR expression measured using qPCR." (PMID 35185785, 2021). "FSHR:c.919G>A SNV affected FSH levels in women with overall endometriosis and the number of oocytes retrieved in those with moderate/severe endometriosis." (PMID 34659133, 2021). "Variants of the FSHB and FSHR genes separately interfered with the hormonal profiles and IVF outcomes of women with endometriosis." (PMID 34659133, 2021). "Discrepancy between expression of FSHR mRNA and protein has also been described for human umbilical vein endothelial cells and endothelial cells in endometriosis samples." (PMID 33374698, 2020). "In the presence of mutant SNP in FSHR gene (680Ser/Ser+680Ser/Asn), mutant SNPs in CYP19 gene demonstrated a significantly decreased risk of endometriosis, indicating that FSHR and CYP19 had synergistic effects on the production of estrogen." (PMID 23139742, 2012). "We also identified an association between mutant genotypes in FSHR, HSD17B3 and CYP19 and decreased risks of endometriosis." (PMID 23139742, 2012). "The higher prevalence of 307Thr of FSHR makes it a highly rational target for drug development in endometriosis therapy." (PMID 23139742, 2012). "The authors found a prominent FSHR-positive vascular pattern in all the endometriosis lesions." (PMID 37174718, 2023). "However, some FSHR and LHR single nucleotide polymorphisms (SNPs) have been observed in endometriosis patients." (PMID 34405378, 2022). "Similarly, endometriosis is a stem cell disease and epithelial progenitors are increased in numbers which express FSHR." (PMID 34717708, 2021). "Moreover, various pathologies like endometriosis, fibroids and endometrial cancers express increased FSHR because they arise due to affected differentiation and selective expansion of FSHR and OCT-4 positive stem/progenitor cells." (PMID 34717703, 2021). "Moreover, the FSHR:c.2039G>A affected FSH levels in women with overall endometriosis, LH levels and total amount of rFSH in those with minimal/mild disease, and number of follicles and number of oocytes retrieved in those with moderate/severe endometriosis." (PMID 34659133, 2021). "Concerning FSHR:c.2039G>A SNV, AA genotype was associated with a higher amount of rFSH for COS in women with minimal/mild disease and a greater number of oocytes retrieved in women with moderate/severe endometriosis." (PMID 34659133, 2021). "A similar discrepancy was observed in endometriosis samples where FSHR at protein level has been shown in endothelial cells of the endometroid tissue, but could not be reproduced by in situ hybridization at mRNA level." (PMID 30778333, 2019). "Expression of FSHR has also been suggested in endometriosis." (PMID 30778333, 2019). "Our results suggest that glycosylated 307Thr of FSHR may mediate extracellular recognition events, which may be important in the development of endometriosis." (PMID 23139742, 2012). "In summary, FSHR with completely wild-type homozygous SNPs at positions 307 and 680 (307Thr/Thr680Asn/Asn) had higher sensitivity to FSH and an increased risk of endometriosis, whereas FSHR possessing at least an allele of mutant SNP at positions 307 and 680 lower risk of endometriosis." (PMID 23139742, 2012). "However, in the presence of mutant SNP in FSHR gene (680Ser/Ser+680Ser/Asn), mutant SNPs in CYP19 gene demonstrated a significantly decreased risk of endometriosis." (PMID 23139742, 2012). "Results of this study suggest that non-synonymous polymorphisms of FSHR, HSD17B3 and CYP19 genes may modulate the risk of endometriosis in Taiwanese Chinese women." (PMID 23139742, 2012).
endometriosis (continued). "Regarding the FSHR:c.2039G>A SNV (rs6166, p.Ser680Asn), women with moderate/severe endometriosis carrying the AA genotype had a significantly higher number of oocytes retrieved than those carrying the GG genotype (p=0.024) in the additive model." (PMID 34659133, 2021). "Considering the FSHR:c.919G>A SNV (rs6165, p.Ala307Thr), women with overall endometriosis carrying the GA genotype had significantly higher serum FSH levels than those with the AA genotype (p=0.032) in the additive model." (PMID 34659133, 2021). "FSHR:c.919G>A affected FSH levels in women with overall endometriosis and the number of oocytes retrieved in those with moderate/severe endometriosis." (PMID 34659133, 2021). "Moreover, the ovarian pattern of differentiation with functional FSH-FSHR system, inducing production of the same steroidogenic cascade as in ovaries has been shown in endometriotic tissues Based on these results, it appears that the expression of FSHR in endometriosis is functional." (PMID 30778333, 2019). "Because these 4 nsSNPs reside in 3 genes related to estrogen synthesis (HSD17B3, FSHR and CYP19), endogenous production of more estrogens, instead of slowing the degradation of estrogens and their metabolites, may be more strongly associated with the risk of endometriosis." (PMID 23139742, 2012). "However, PAPP was not correlated with FSHR in endometriosis women, like what has been found in poor responder patients." (PMID 39493123, 2024). "There is no convincing evidence to link FSH/FSHR gene with endometriosis." (PMID 34717708, 2021). "Moreover, the FSHR:c.2039G>A SNV affected FSH levels in women with overall endometriosis, LH levels and total amount of rFSH in those with minimal/mild disease, and number of follicles and number of oocytes retrieved in those with moderate/severe endometriosis." (PMID 34659133, 2021). "Our results did not identify endometriosis-specific amino acid changes in HSD17B1 but detected endometriosis preferential structural changes of HSD17B3, CYP19, and FSHR." (PMID 23139742, 2012).
ovarian hyperstimulation syndrome (17 papers, 2013 to 2026). A complication of ovulation induction in infertility treatment. "Spontaneous ovarian hyperstimulation syndrome (OHSS) is closely associated with follicle stimulating hormone receptor (FSHR) functional mutations." (PMID 42085637, 2026). "Case 30 had a homozygous c.1540 T>C mutation of the FSHR and she developed ovarian hyperstimulation syndrome during ovarian stimulation." (PMID 40171200, 2025). "Mutations in the human FSHR gene cause ovarian dysgenesis type 1, and also the ovarian hyperstimulation syndrome (OMIM 136435)." (PMID 34217202, 2021). "Spontaneous ovarian hyperstimulation syndrome (sOHSS) is a rare event that may result from a FSH-producing pituitary adenoma (FSHoma), activating mutations of the FSH receptor (FSHR), and cross-reactivity of the FSHR to elevated hCG and TSH in the setting of pregnancy or hypothyroidism." (PMID 24058690, 2013). "These SNPs influence FSHR protein responsiveness to exogenous FSH, and have been shown to affect the success of in vitro fertilization treatment as well as the likelihood of developing severe ovarian hyperstimulation syndrome (OHSS)." (PMID 41393297, 2025).
prostate carcinoma (17 papers, 2013 to 2025). A carcinoma that arises from epithelial cells of the prostate gland. "FSHR is a tumor-associated antigen present in OC, prostate cancer, and the neovessels of 80% of cancers." (PMID 36509287, 2022). "FSHR expression was generally higher in prostate cancer samples than in normal prostate and BPH samples." (PMID 41347146, 2025). "The first study to use a genome-wide approach reported a significant association between an SNP (rs2268363) in the follicle-stimulating hormone receptor (FSHR) gene and the development of erectile dysfunction after radiotherapy for prostate cancer." (PMID 39851963, 2025). "FSHR expression was found to be low-to-undetectable in normal prostate tissue and in benign prostatic hyperplasia, and consistently high in prostate cancer tissue." (PMID 37375761, 2023). "We also observed bands between 50 and 65 kDa using the FSHR323 antibody, however, 87 kDa FSHR band was reported in human ovary and prostate cancer cells using this antibody." (PMID 33374698, 2020). "Previous studies have documented the overexpression of FSHR in human prostate cancer tissues, particularly in relation to hormone-resistant prostate tumors." (PMID 29097913, 2017). "FSHR expression is observed in androgen-independent prostate cancer cells which are considered as less differentiated than androgen – dependent ones." (PMID 25685198, 2015). "In contrast, for prostate cancer metastases, the density of FSHR-positive vessels was about 3-fold higher at the exterior of the tumor compared to the interior." (PMID 23688201, 2013). "The negative results of Fshr mRNA expression in the endothelial cells of LNCaP xenograft murine vessels, supported by the negative expression of FSHR in HUVECs, indicate that FSHR expression in the prostate cancer vasculature, as a potential therapeutic target, requires further confirmation." (PMID 40490708, 2025). "Under pathological conditions, FSHR has been found in granulosa cell tumors, ovarian surface epithelial carcinomas, ovarian Sertoli-Leydig cell tumors, prostate cancer, endometrial cancer, neuroendocrine tumors in the appendix, and normal fat tissue." (PMID 40490708, 2025). "By using immunoelectron microscopy we demonstrated that, in a mouse tumor model for human prostate cancer, FSHR is present on the luminal surface of the tumor ECs and can specifically bind and internalize anti-FSHR antibodies coupled to colloidal gold particles delivered in the circulation." (PMID 33920299, 2021). "FSH and FSHR expression in prostate cancer cells, PC-3 and DU-145 cell lines." (PMID 30778333, 2019). "Furthermore, FSHR may be relevant in prostate cancer progression, given its dense expression at the periphery of tumors." (PMID 37375761, 2023). "However, in four prostate cancer samples, the epithelium of tumor-adjacent normal or hyperplastic prostate glands (all samples included areas of adjacent normal prostate tissue) focally exhibited a strong cytoplasmic anti-FSHR staining." (PMID 31548530, 2017). "In the prostate cancer FSHR-positive arterioles, capillaries and venules (but not lymphatic vessels) were located at the periphery of the tumor core." (PMID 30778333, 2019). "Our studies could not confirm the previously reported FSHR overexpression in ovarian and prostate cancer cells." (PMID 31548530, 2017). "None of the 30 prostate cancer samples showed FSHR staining of the tumor cells." (PMID 31548530, 2017). "Furthermore, the authors confirmed their earlier reports on specific overexpression of FSHR in peripheral tumor blood vessels but could not repeat the previously reported FSHR overexpression in ovarian and prostate cancer cells." (PMID 30778333, 2019).